FOXO1 (forkhead box O1)
Diseases named in the same sentence as FOXO1 in open-access papers (continued):
Sharing a sentence is not in itself a finding about the gene and the disease.
cancer (continued). "Thus, upregulation of RUNX2 or FOXO1 may alternatively favor fatty acid metabolic pathways to promote cancer proliferation." (PMID 35851595, 2022). "FOXO1, an important member of the FOXO subfamily in the FOX family, encodes a transcription factor and has been reported to be involved in various physiological processes, including inducing cancer cell cycle arrest and suppressing the migration and invasion of cancer cells." (PMID 36092919, 2022). "Depletion of FOXO1 could promote cancer cell proliferation by enhancing cyclin D1 expression." (PMID 36210843, 2022). "Thus, the activation of FOXO1 is regarded as a therapeutic strategy for cancer." (PMID 36539739, 2022). "Thus, cancer‐induced muscle wasting could be mediated, at least in part, through a FoxO1–FoxP1‐dependent mechanism." (PMID 33527776, 2021). "Furthermore, they demonstrated that co-culturing 3TL-L1 adipocytes overexpressing miR-27a with HepG2 cancer cells downregulated forkhead box protein O1 (FOXO1) and promoted G1/S cell cycle transition in HepG2 cells by decreasing p21 and p27 and increasing cyclin D1 levels." (PMID 34283044, 2021). "At the same time, these triple-FOXO1/3/4-deficient animal studies also reveal that the FOXO isoforms have overlapping functions in distinct biological functions in specific tissues, and that FOXO proteins are associated with cancer progression, metastasis and angiogenesis." (PMID 32372224, 2020). "Therefore, FoxO1 may be a key player in the communication between mitochondria and the nucleus in cancer cells for the maintenance of oxidative metabolism through mitochondrial quality control." (PMID 31819175, 2020). "Based upon our findings in this study and previous reports, we hypothesized that co-treatment with GSK126 and taxane can induce robust death even in PTEN-negative cancer cells through increasing FOXO1 expression (by GSK126) and nuclear localization (by taxane)." (PMID 31410199, 2019). "Thus, FoxO1 is expected to be a potential target for anti-cancer drugs." (PMID 31767027, 2019). "Moreover, FoxO1 may negatively regulate SREBP1c-mediated fatty acid and cholesterol biosynthesis, which are up-regulated in cancer, by occupying and disrupting the assembly of the transcriptional initiation complex on the SREBP1c promoter." (PMID 29865240, 2018). "FoxO1 expression was distinctively upregulated in paclitaxel resistant cell line and enhanced by exposure to paclitaxel with subcellular translocation; in addition, FoxO1 overexpression was frequently observed in cancer tissue samples from chemoresistant patients." (PMID 25566078, 2014). "Although we cannot ascertain, based on our findings, whether FoxO1 or FoxO3a directly induce Cebpb gene transcription during cancer cachexia, there are two putative FBEs located within the Cebpb proximal promoter that FoxO1 has previously been documented to bind." (PMID 25539728, 2014). "In the case of autophagy, acetylation promotes autophagy in cancer through modifications of PAK1 and FOXO1, an effect that can be reversed by inhibition of PAK1 or FOXO1." (PMID 41303712, 2025). "By regulating the expression of FOXO1 and CD38, inactivating SRSF1 in T cells dramatically increases the cytotoxicity of CD8 + T cells in malignancies." (PMID 39837814, 2025).
cancer (continued). "Through the deacetylation of transcription factors like FOXO1 and NF-κB, SIRT1 suppresses the expression of pro-inflammatory cytokines and antigen-presenting machinery, thereby promoting immune evasion in cancer." (PMID 41008982, 2025). "Prior studies have confirmed that miR-181a directly targets FOXO1 and PDCD4 and that its suppression increases apoptotic sensitivity in various cancers." (PMID 41462911, 2025). "Focusing on 14-3-3ζ which was reported to be highly expressed in various cancers, we found that BA also inhibited the binding of 14-3-3ζ to TSC2, Rictor, Raptor, mTOR, FOXO1, FOXO3a, and STAT3." (PMID 40316727, 2025). "In the pan‐cancer ICI cohort, patients were stratified into FOXO1 high‐ and low‐expression groups based on the average level of FOXO1 expression." (PMID 38899748, 2024). "Overall, our findings determine FOXO1 as a novel molecular target of UroA in CD8+ T cells and indicate UroA as promising immunomodulator to improve cancer immunosurveillance." (PMID 38626334, 2024). "On the contrary, some core kinases and transcription factors involved in cancer such as CDK6, ERBB2, JAK1, DAPK1, FOXO1, and RXRA were highly expressed in S-III." (PMID 38143770, 2023). "FOXO subfamily genes include FOXO1, FOXO3, and other subtypes, which mainly regulate metabolism, antioxidant stress, and cell cycle progression, and are mostly related to cancer and diseases of the immune system." (PMID 36819781, 2023). "To explore the biological function of circHERC1 in vivo, we subcutaneously inoculated NCI-H3255 cancer cells with altered expression of circHERC1, HMGB1 or FOXO1, into the flanks of nude mice." (PMID 37932766, 2023). "FOXO1 induction using 4‐OHT also led to cell cycle arrest and apoptosis, highlighting canonical FOXO roles in cancer." (PMID 37584250, 2023). "FOXO1 and FOXO3 have been reported to regulate germ cells, neural stem cells, hematopoietic stem cells, muscle satellite cells, and cancer stem cells." (PMID 36881352, 2023). "We also found a time-dependent activation of stress-responsive kinases p38 and an increased level of Foxo1, a p300/CBP regulated, ROS-responsive transcription factor required for autophagy in cancer cell lines." (PMID 36117234, 2023). "To date, such molecular pathways are known that regulate the expression and activity of NAMPT in cancers, such as c-MYC/NAMPT/SIRT1, HMGA1/NAMPT/NAD+, FOXO1/NAMPT, NAMPT/miRNA, SIRT6/SIRT1/NAMPT, C/EBPβ/NAMPT." (PMID 37175631, 2023). "According to the previous studies, FOXO1 mainly plays a protective factor in various cancers, especially in TNBC, which is consistent with our investigations and intensely confirmed the positively correlated expression alterations of FOXO1 and LYPLAL1-DT." (PMID 38111678, 2023). "Subsequent work by our group and others revealed that the forkhead box transcription factor FOXO1 also helped induce stem gene expression in examined BBC and GBM cell lines, highlighting conserved mechanisms in ESCs and cancer cells." (PMID 36602390, 2023). "Treated with Ro5-3335, a RUNX1-CBFβ interaction inhibitor, the level of p-FOXO1Ser256 and Bcl-2 were significantly changed in control cancer cell lines (SKOV3, OVCAR3), meanwhile the expression level of FOXO1 was almost unchanged after Ro5-3335 treatment." (PMID 38057816, 2023). "MRNA expression of SPP1, VEGFA, POSTN, CD44, FOXO1, and RUNX2 genes was significantly change with the cancer stages of the patients." (PMID 36424413, 2022). "We also present new insights into the role of FOXO1 in the DXM-21-P- and BTM-21-P-induced expression of TTP in cancer cells." (PMID 36430156, 2022).
cancer (continued). "This work, for the first time, attributed the anti-cancer efficacy of CAP to its selectivity against cancer stemness, and proposed the AQP3/SCAF11/FOXO1 axis in mediating this process." (PMID 35637961, 2022). "We propose CAP as a 'selective' onco-therapeutic against cancer stemness, with the AQP3/FOXO1 axis being one molecular mechanism." (PMID 35637961, 2022). "For example, a high expression level of FOXO1 and FOXO3 has been found to be related to cancer metastasis and a matrix metalloproteinase (MMP) upregulation." (PMID 36555288, 2022). "FOXO1 is required for inducible autophagy in cancer cells, where SIRT2 deacetylates FOXO1 and forms a complex with SIRT2." (PMID 36712965, 2022). "miR-1269a can regulate the occurrence and development of cancer by targeting downstream genes (CXCL9, SOX6, FOXO1, ATRX, RASSF9, SMAD7, HOXD10, and VASH1)." (PMID 35252180, 2022). "For example, a high expression level of FOXO1 and FOXO3 has been found to be correlated with cancer metastasis and an MMP upregulation." (PMID 36555288, 2022). "Upregulated expressions of E2A, FOXO1, or FOXP1 enhanced RAG1 expression, while silencing of E2A, FOXO1, or FOXP1 decreased RAG1 expression in the cancer cells." (PMID 34226529, 2021). "Numerous cell signaling pathways are involved in the initiation and progression of cancer cachexia, including the TNF-ɑ pathway, TGFβ/p38/MAPK pathway, NFκB pathway, IL-6 pathway, IGF/Akt pathway and FOXO1/FOXO3a pathway, among others." (PMID 34724970, 2021). "Forkhead box O1 (FOXO1) is known as an anoikis-promoting cellular factor and suppresses the anchorage-independent growth of cancer cells." (PMID 33435156, 2021). "Integrin subunit α2 (ITGA2) is an oncogene factor which promotes metastasis and growth ability of cancer cells and it is thought to reduce sensitivity of cancer cells of PTX through activation of Akt/FoxO1 signaling pathway." (PMID 33644048, 2021). "The transcription factor FoxO1 (Forkhead box O, FOXO) is a downstream target in the IGF-1R PI3K/Akt pathway involved in several physiological and pathological processes, including cancer development." (PMID 34202122, 2021). "The FOXO transcription factor family contains four highly relevant members, namely, FOXO1, FOXO3a, FOXO4, and FOXO6, which are direct downstream targets of AKT and play important roles in cancer progression." (PMID 34183647, 2021). "FOXO1 has been proposed to play an essential role in PI3K/AKT signaling and regulate many biological activities in cancers." (PMID 34035814, 2021). "Among 4 mammalian FOXO members (FOXO1, -3, -4, -6), FOXO3 has a predominant role in controlling cancer development." (PMID 31903146, 2020). "AURKA has also been shown to negatively regulate FOXO1 at the transcriptional level, indicating that FOXM1 can indirectly regulate FOXO expression via AURKA to sustain its expression and activity in cancer cells." (PMID 32372224, 2020). "The metastasis suppressor gene nm23-H1 is involved in restricting the progression of a number of human cancers, including non-small cell lung cancer (NSCLC), and has also been shown to be positively regulated by FOXO1 in lung cancer." (PMID 32372224, 2020). "HepG2 treated with CS3 greatly increased expression of Foxo1 and Beclin-1, confirming the induction of CS3 in cancer cell apoptosis and autophagy." (PMID 31892846, 2020). "In cancer cells, PPARγ co-activator 1α (PGC-1α) interacts with FOXO1 and acts as a co-activator in hepatocytes for activation of gluconeogenic genes." (PMID 32372224, 2020). "MAPK signalling pathway (JUN, RAC1, MAPK8, MYC and FOS) and transcriptional misregulation in cancer (CDKN1A, MYC and FOXO1)." (PMID 32457348, 2020). "Specifically, high FOXO1 and FOXO3 expression has been correlated with matrix metalloproteinase (MMP) upregulation and enhanced cancer metastasis." (PMID 32372224, 2020).
cancer (continued). "CB stimulates the sensitivity of NPC cells to CP therapy by activating FOXO1 and subsequently inhibiting MYH9, which leads to a reduction in cancer rigidity and inhibition of EMT (E-cadherin upregulation, and N-cadherin downregulation)." (PMID 32503307, 2020). "High dose of perifosine (10 μM) inhibited cancer cell proliferation and phosphorylation of AKT and its downstream targets, FOXO1 and GSK-3β13,14." (PMID 31113933, 2019). "Transcription factors forkhead box protein O1 (FOXO1) and paired box 3 (PAX3) have been reported to play important roles in various cancers." (PMID 31823759, 2019). "Investigating the mechanisms related to the cellular activity of FOXO1 and PAX3 will likely contribute to the development of cancer therapies." (PMID 31823759, 2019). "Targeting the PI3K/AKT pathway and its downstream targets like FOXO1 and GSK3 appears to be an attractive approach to treat cancers that are known to have aberrant AKT activation." (PMID 30934922, 2019). "This identified ATF4, FOXO1, HIF1A, MAF, MYC, and SREBP1 in FGFR-dependent cancer cells whereas ATF4 and MYC in EGFR-addicted cancer cells, which were required for the transcription of the signature genes in glycolysis or SSP." (PMID 31221965, 2019). "Further studies showed that GOLPH3 promotes the development of cancer by activating mammalian target of rapamycin (mTOR) signaling, enhancing AKT activity, and decreasing forkhead box O1 (FOXO1) transcriptional activity." (PMID 31737112, 2019). "To explore the effect of E1A on FoxO1 expression, we overexpressed E1A in E1A-negative rodent (NIH3T3, REF52) and human cancer cells (HCT116)." (PMID 31906031, 2019). "Our previous studies demonstrated that FOXO1 is significantly down-regulated in PDAC tissues, which is correlated with cancer cell stemness in PDAC." (PMID 31027497, 2019). "To further verify the regulation of FOXO1 expression by EZH2, we treated C4-2 and 22Rv1 cell lines with histone deacetylase (HDAC) inhibitor SAHA, an FDA approved drug for cancer treatment." (PMID 31410199, 2019). "Similar with DUSP5, FOXO1 is recently found to inactivate MAPK signaling pathway through impeding ERK1/2 phosphorylation, leading enhanced chemosensitivity of cancer cells." (PMID 29341479, 2018). "The downregulated genes were associated with cell cycle, TGF-β signaling, FoxO signaling, HIF-1 signaling, and cancer (CDKN1B, FLT3, PDK1, FOXO1, BCL2, ERG), suggesting potential positive regulation of these pathways by SHARP1 to maintain MLL-AF6 AML activity." (PMID 29692408, 2018). "It has been demonstrated that the expression of FOXO1 and C-myc is regulated by AKT1 and Erk1/2 through the PI3K/AKT and MAPK/ERK signaling pathways in various human carcinomas." (PMID 29636108, 2018). "The genes that were shared by three different cancers (i.e., FGFR3, EPAS1, SRC, and FOXD3) are shown in coral, and the genes that were shared by two types of cancers (i.e., PPARG, FOXO1, CDK4, NKX3-1, PIK3R1, PRKCB and EDNRB) are shown in light pink." (PMID 28178311, 2017). "The NFYB/E2F1 complex becomes connected with FOXO1/3 and is the factor of the FOXO- dependent signaling cascade, which is activated in the cells of different cancers." (PMID 28031533, 2017). "The miR-27 displays its oncogenic property through regulating the expression of target genes including FOXO1, BTG2, PHB and other cancer-related genes." (PMID 28415619, 2017).
cancer (continued). "The research presented herein places miR-486-5p in the pantheon of prominent cancer genes that includes PTEN and FOXO1." (PMID 29069829, 2017). "Above all, these results suggest that ESR1, FOXO1, CXCL12, and GNAO1 are involved in the pathogenesis of carcinoma by affecting cell division, complement activation, and protein activation cascades, which support our findings." (PMID 28302149, 2017). "Within the down-regulated signaling pathways, there were ubiquitin-mediated proteolysis, mTOR signaling, pathways in cancer, RIG-like receptor signaling pathway with Herc1 and Traf6, Mapk1 and Rps6ka3, Ifg1r, Prkx, and Foxo1 as the core regulatory factors." (PMID 26900402, 2016). "miR-182-5p promotes T cell-mediated immune responses by inhibiting forkhead box protein O1 (FOXO1), a gene that is also targeted by miR-21 in cancer." (PMID 26529003, 2015). "In cancer cells, NFIL3 was found to block FOXO1 access to cell death genes, potentially allowing FOXO1 to drive pro-oncogenic programs, a true paradigm shift for the PI3K pathway." (PMID 26539561, 2014). "In contrast to FOXO1, FOXM1 shows oncogenic activities and targeting FOXM1 induces apoptosis in cancer cells." (PMID 25010679, 2014). "We found two major types of complexes that are affected by miRNAs during cancer progression; the first contains SMAD3, SMAD2, SMAD4, SMAD6, FOXO1, HOXC8, and SKIL, which are connected to AKT1, which is in turn a key modulator of TGF-B signaling pathway." (PMID 24391925, 2013). "We found that E2A, FOXO1 and FOXP1 were expressed in cancer cells and localized to the nuclei of these cells." (PMID 21655267, 2011). "RT-PCR results showed that FOXO1, FOXP1, NF-κB subunit p65 and both of the two isoforms of E2A (E47 and E12), were expressed in the cancer cells A549, PC3, MCF-7 and MDA-MB-231." (PMID 21655267, 2011). "Similar to their role in the activation of RAG expression in B cells, we found that E2A, FOXO1 and FOXP1 regulated RAG expression in cancer cells by binding to Erag." (PMID 21655267, 2011). "In vivo chromatin immunoprecipitation (ChIP) assay showed that the histone H3 of Erag was acetylated and that E2A, FOXO1, FOXP1 were bound to Erag in these cancer cells." (PMID 21655267, 2011). "In this network, many of the cancer-affected target mRNAs were mainly regulated by the transcription factors MYCN and FOXO1 which play a vital role in cell death, apoptosis, proliferation and survival." (PMID 21595958, 2011). "In this study, we first analyzed the protein and mRNA expressions of those transcription factors that have been found to be essential for RAG activation in B cells, including E2A (E47 and E12), FOXO1, FOXP1, Ikaros, NF-κB, and PAX5β, in four cancer cell lines." (PMID 21655267, 2011). "By RT-PCR, Western blot and immunofluorescence, we found that transcription factors E2A, FOXO1 and FOXP1 were expressed and localized to the nuclei of these cancer cells." (PMID 21655267, 2011). "At the protein level, E2A, FOXO1, FOXP1 and NF-κB subunit p65 were all detected in the cancer cells with Western blot assay." (PMID 21655267, 2011). "Here we have shown that FOXO1 and FOXP1 also have regulatory function in RAG expression in cancer cells." (PMID 21655267, 2011). "Forkhead Box-O (FOXO-1), a downstream target of AKT is emerging as a key regulator of cell survival in various cancers." (PMID 21931821, 2011). "We have previously shown that PI3′-kinase/AKT signaling plays a pivotal role in pathogenesis of DLBCL and other cancer cells by activating AKT and it's down stream targets, FOXO-1, GSK-3 and Bad." (PMID 21931821, 2011). "In this study, we focused on a selected number of transcription factors and found that E2A, FOXO1 and FOXP1 regulated RAG expression in cancer cells." (PMID 21655267, 2011).